GPR39 (G protein-coupled receptor 39)
Description:
Zinc-sensing receptor that can sense changes in extracellular Zn(2+), mediate Zn(2+) signal transmission, and participates in the regulation of numerous physiological processes including glucose homeostasis regulation, gastrointestinal mobility, hormone secretion and cell death. Activation by Zn(2+) in keratinocytes increases the intracellular concentration of Ca(2+) and activates the ERK/MAPK and PI3K/AKT signaling pathways leading to epithelial repair. Plays an essential role in normal wound healing by inducing the production of cytokines including the major inflammatory cytokine IL6 via the PKC/MAPK/CEBPB pathway (By similarity). Regulates adipose tissue metabolism, especially lipolysis, and regulates the function of lipases, such as hormone-sensitive lipase and adipose triglyceride lipase (By similarity). Plays a role in the inhibition of cell death and protects against oxidative, endoplasmic reticulum and mitochondrial stress by inducing secretion of the cytoprotective pigment epithelium-derived growth factor (PEDF) and probably other protective transcripts in a GNA13/RHOA/SRE-dependent manner. Forms dynamic heteroreceptor complexes with HTR1A and GALR1 depending on cell type or specific physiological states, resulting in signaling diversity: HTR1A-GPR39 shows additive increase in signaling along the serum response element (SRE) and NF-kappa-B pathways while GALR1 acts as an antagonist blocking SRE.
Synonyms: ZnR
Tractability: Small molecule: a high-quality ligand is known; it belongs to a druggable protein family. Antibody: UniProt places it where antibodies can reach, with high confidence; its Gene Ontology location is reachable by antibodies, with high confidence; UniProt predicts a signal peptide or a membrane-spanning region. PROTAC: a small molecule that binds it is known.
Target class: Family A G protein-coupled receptor; Membrane receptor
Chemical probes: CHEMBL3092413, TC-G-1008 (high quality)
Gene: Protein-coding gene on chromosome 2 (132,416,805 to 132,646,582, forward strand). Ensembl gene ENSG00000183840.
Subcellular location: Cell membrane
Pathways (Reactome):
Signal Transduction: Class A/1 (Rhodopsin-like receptors); G alpha (q) signalling events; G alpha (s) signalling events
Gene Ontology:
Molecular function: protein binding; G protein-coupled receptor activity
Biological process: G protein-coupled receptor signaling pathway
Cellular component: plasma membrane; membrane
Genetic constraint (gnomAD): Loss-of-function variants: 23 observed, 19.69 expected, observed/expected ratio (o/e) 1.17, 90% interval 0.84 to 1.64. The upper end of that interval is the gene's LOEUF score, 1.64, which puts it in group 6 of 6, group 1 being the genes least tolerant of losing a copy. Missense variants: 647 observed, 636.24 expected, observed/expected ratio (o/e) 1.02, 90% interval 0.95 to 1.09. Synonymous variants: 280 observed, 273.79 expected, observed/expected ratio (o/e) 1.02, 90% interval 0.93 to 1.13.
Homologues: Orthologues: chimpanzee GPR39 (99% identical), macaque GPR39 (94% identical), mouse Gpr39 (82% identical), pig GPR39 (82% identical), rat Gpr39 (81% identical), rabbit GPR39 (80% identical), dog GPR39 (74% identical), guinea pig GPR39 (53% identical), zebrafish gpr39 (41% identical). Paralogues in human: NTSR1 (24% identical), NMUR1 (23% identical), MLNR (21% identical), NTSR2 (21% identical), NMUR2 (20% identical), GHSR (19% identical), EDNRB (15% identical), TRHR (15% identical), NMBR (15% identical), EDNRA (14% identical), BRS3 (14% identical), GRPR (14% identical), and 3 more.
Diseases named in the same sentence as GPR39 in open-access papers:
GPR39 is named in the same sentence as 70 diseases in open-access papers, as found by Europe PMC text mining. Sharing a sentence is not in itself a finding about the gene and the disease. The quoted sentences say what the papers report.
depression (17 papers, 2017 to 2025). "Deficiency in GPR39 is linked to depression-like symptoms and a higher risk of Alzheimer’s disease, both of which are closely connected to sleep disorders." (PMID 39416650, 2024). "Changes in ZnR/GPR39 expression levels arising from Zn deficiency have also been observed in studies of depression and are related to behavioral manifestations; dietary interventions with Zn successfully alleviated symptoms." (PMID 36902254, 2023). "GPR39 has also been implicated in a variety of neurological and neuropsychiatric disorders, including AD, depression, anxiety, and seizures." (PMID 35875352, 2022). "BDNF has been widely implicated in depression disorders, and zinc activation of GPR39 leads to increased BDNF via the Gαs pathway and CRE-dependent transcription." (PMID 34360964, 2021). "G-protein associated proteins are strongly represented such as the GPR39 gene (G protein-coupled receptor 39) involved in, zinc-dependent signaling in epithelial tissue in intestines, prostate, salivary gland secretion and pathophysiology of depression." (PMID 40560842, 2025). "Subsequently, we analyzed the SNPs significantly associated with heart failure identified in the present study and observed that the expression of GPR39 corresponding to rs72844714 decreased in the hippocampus and cortex of patients with depression." (PMID 38656892, 2024). "In contrast, rats with depressive behaviors due to olfactory bulbectomy showed increased GPR39 in hippocampus, perhaps suggesting a regional difference in GPR39-related depression or a compensatory or protective response in hippocampus to the depressive state." (PMID 34360964, 2021). "Perturbation of glutamate signaling in depression models also reveals additional aspects of GPR39’s effect." (PMID 34360964, 2021). "GPR39 plays an important role in wound healing, depression, inflammatory bowel diseases, alcohol use disorder, insulin secretion and several cancers." (PMID 34645465, 2021). "GPR39’s ligand, zinc, has been repeatedly studied as a potential treatment for depression and anxiety." (PMID 34360964, 2021). "Changes in ZnR/GPR39 expression were also shown following treatment with monoaminergic inhibitors, such as used to treat depression, thus suggesting a link between the receptor and this disease." (PMID 29389900, 2018). "Several studies reported a role for ZnR/GPR39 in depression, based on apparent changes in the expression level of this receptor following Zn2+-deficiency that were correlated with behavioral changes, also in suicide victims." (PMID 29389900, 2018). "New evidence suggests that GPR39 plays a significant role in the development of depression." (PMID 39684342, 2024). "Transgenic mice with deleted GPR39 gene showed a depression- and anxiety-like phenotype." (PMID 39684342, 2024). "If GPR39 is necessary to maintain the regulation of neuronal excitability, then drugs targeting GPR39 could affect two or more neurotransmitter systems simultaneously to control depression." (PMID 36942516, 2023). "Furthermore, interfering with the expression of GPR39 can affect or even become a target for treating epilepsy, depression, and diarrhea." (PMID 36942516, 2023). "Notably, the synergistic interaction among low serum zinc concentrations, GPR39, BDNF, and serotonergic system may be an underlying mechanism of depression." (PMID 37434135, 2023). "GPR39 deficiency may abolish these monoaminergic-based antidepressant effects since GPR39 KO mice do respond to treatment with the selective serotonin reuptake inhibitor (SSRI), escitalopram, in a forced-swim depression assay." (PMID 34360964, 2021). "Indeed, GPR39 seems to be involved in many important metabolic and endocrine functions, but also to play a part in inflammation, cardiovascular diseases, saliva secretion, bone formation, male fertility, addictive and depression disorders and cancer." (PMID 33918078, 2021).
depression (continued). "The G protein-coupled receptor 39 (GPR39) is responsive to zinc levels, and its activation influences pathways involved in depression." (PMID 40390089, 2025). "Mice lacking GPR39 display behaviors, seen in depression and anxiety, accompanied by compromised muscle coordination." (PMID 40390089, 2025). "The involvement of GPR39 in these pathways through mechanisms such as zinc-mediated neurotransmission and neuroplasticity provides further support for its therapeutic potential in addressing the overlapping pathophysiology of OAB and depression." (PMID 39684342, 2024). "These insights reinforce the need for further research into how to target GPR39 and its downstream pathways, which could advance treatment strategies for OAB with comorbid depression." (PMID 39684342, 2024). "When zinc attaches to its sensing receptors, which are GPR39, it activates the downstream cyclic MP-response element, dependent on gene transcription, resulting in high levels of brain-derived neurotrophic factor (BDNF) in specific brain regions, ultimately decreasing depression." (PMID 38690099, 2024).
epilepsy (11 papers, 2018 to 2024). A brain disorder characterized by episodes of abnormally increased neuronal discharge resulting in transient episodes of sensory or motor neurological dysfunction, or psychic dysfunction. "GPR39 is expressed in regions implicated in Alzheimer’s disease, epilepsy, and neuropsychiatric disorders, such as the frontal cortex, amygdala, and hippocampus." (PMID 34360964, 2021). "Zinc deficiency has been linked to epilepsy and seizures, which suggests an important physiological role for ZnR/GPR39." (PMID 33255662, 2020). "Activation of GPR39 by TC-G 1008 facilitated the development of epileptogenesis in the pentylenetetrazole (PTZ)-induced kindling model of epilepsy." (PMID 36672199, 2023). "The ZnD diet abolished the chronic effects of TC-G 1008 on the maximal seizure score and the percentage of fully kindled mice in the PTZ-kindling model of epilepsy, thus showing that dietary zinc is an important modulator of the effects mediated by GPR39." (PMID 36672199, 2023). "Using the same method, we previously did not observe significant changes in total zinc in the hippocampus of GPR39 KO mice subjected to the PTZ-kindling model of epilepsy." (PMID 36672199, 2023). "At present, the mainstream view is that GPR39 inhibits the occurrence of epilepsy by regulating the change in membrane potential." (PMID 36942516, 2023). "In this study we used samples obtained from mice that were subjected to models of acute seizures or a chronic model of epilepsy, as an example of a research area in which GPR39 is being investigated." (PMID 35805072, 2022). "The importance of GPR39 in neurotransmission and the maintenance of hippocampal baseline excitatory tone positions it to play a role in epilepsy." (PMID 34360964, 2021). "Our data argue against GPR39 activation being a viable therapeutic strategy for treating epilepsy and suggest investigating whether TC-G 1008 is a selective agonist of the GPR39 receptor." (PMID 37185787, 2023). "Replication was of crucial importance because the prevailing hypothesis was that GPR39 activation is a new therapeutic strategy for treating acute seizures/epilepsy, while our results are contrary to this hypothesis." (PMID 36672199, 2023). "A link between GPR39 and seizures/epilepsy has been suggested in a few studies." (PMID 35805072, 2022). "Importantly, ZnR/GPR39 activity was shown to enhance neuronal inhibitory tone, and zinc deficiency is associated with epilepsy and seizures, suggesting the significant physiological role of ZnR/GPR39." (PMID 29389900, 2018). "Moreover, activating GPR39 shows promise as a potential treatment approach for epilepsy." (PMID 39684342, 2024). "Replication was necessary as aggravation of either acute seizures or the chronic process of epilepsy development by a compound acting at GPR39 is contrary to the prevailing hypothesis on GPR39 activation being a potential new therapeutic strategy for treating seizures/epilepsy." (PMID 36672199, 2023). "Epilepsy is among the diseases that may find a cure by targeting the GPR39 protein." (PMID 37185787, 2023). "Thus, GPR39 may potentially contribute to disorders of neural circuit over-excitability, such as epilepsy and chronic pain." (PMID 34360964, 2021). "Thus, by regulating neuronal excitability, ZnR/GPR39 activity can limit neuronal firing and consequently may play a role in epilepsy development and progression." (PMID 33202963, 2020). "The results showing regulation of Cl− transport by ZnR/GPR39 activation of KCC2, taken together with the prominent role of loss of KCC2 function in increasing seizure susceptibility, suggested that ZnR/GPR39 may play a role in epilepsy via this pathway." (PMID 29389900, 2018). "GPR39 can modulate the excitatory activity of KCC2, thereby regulating neuronal electrical activity, which is important for epilepsy control." (PMID 36942516, 2023). "Therefore, GPR39 may serve as a therapeutic target for epilepsy." (PMID 36942516, 2023).
epilepsy (continued). "Pharmacologic targeting of GPR39 may prove effective in disorders characterized by dysregulated neural circuits and neurotoxicity from hyperexcitability, with potential for modulating epilepsy, inflammation, pH dysregulation, chronic pain, and neuropsychiatric disorders." (PMID 34360964, 2021). "The relationship between GPR39 and magnesium homeostasis has not yet been examined, nor has such a relationship in the context of seizures/epilepsy." (PMID 35805072, 2022). "Furthermore, the role of the GPR39 gene in the development of epilepsy, i.e., epileptogenesis, has not been examined." (PMID 37185787, 2023). "Our data do not support the hypothesis that GPR39 mediates total magnesium levels in the hippocampus in the PTZ kindling model of epilepsy." (PMID 35805072, 2022).
Zinc deficiency (10 papers, 2017 to 2023). A deficiency of the essential metal Zinc; an essential cofactor for many enzymes. "In accordance with decreased zinc intake, marginal zinc deficiency also reduced serum zinc levels and the relative expression of GPR39 in ETEC uninfected mice." (PMID 36136723, 2022). "Zinc deficiency and decreased expression of the zinc sensing receptor G-protein-coupled receptor 39 (GPR39) are associated with MDD." (PMID 35207483, 2022). "We hypothesized that the effects would differ under the condition of zinc deficiency, when there would be a reduced supply of the presumed endogenous agonist of GPR39—the essential element zinc." (PMID 36672199, 2023). "In zinc deficient animals, the heterodimer 5-HT1a-GalR1 is pathologically observed due to a decrease in GPR39 expression and, thus, may reflect a phenotype of the zinc deficiency." (PMID 34360964, 2021). "Since GPR39 expression is closely tied to zinc levels, with zinc deficiency commonly observed in alcoholics, the downregulation of GPR39 may reflect decreased zinc levels." (PMID 34360964, 2021). "Indeed, zinc deficiency correlates with increased neurologic and psychiatric disorders; since GPR39 expression decreases with zinc deficiency, GPR39 is likely implicated in the pathogenesis of these disorders." (PMID 34360964, 2021). "Further studies are needed to elucidate changes within the immune system of GPR39 knockout mice as well as effects of antidepressants on zinc deficiency-induced and GPR39-knockout-induced immune alterations, that may be linked to neural plasticity events." (PMID 28299207, 2017). "Interestingly, GPR39 deficiency is associated with impaired bone composition in mice and zinc deficiency reduces bone mineral density in rats, which may indicate the role of zinc in the bone–vascular axis." (PMID 34831306, 2021). "Marginal zinc deficiency aggravating the intestinal injury in mice was likely to be associated with NF-κB, but it did not correlate with the zinc-receptor GPR39." (PMID 36136723, 2022). "Moreover, marginal zinc deficiency failed to change the host’s zinc levels, as evidenced by the fact that the serum zinc levels and zinc-receptor GPR39 expression in jejunum were not significantly different in mice with ETEC challenge." (PMID 36136723, 2022).
diabetes (9 papers, 2011 to 2025). "Most studies have focused on the role of GPR39 in diabetes, psychiatric disorders, and intestinal diseases." (PMID 36942516, 2023). "In a rat model of diabetes, GPR39 was found to play a potential regulatory role in lipid homeostasis, as a high level of its expression was observed in the adipose tissue of obese rats and rats with type 2 diabetes." (PMID 34288802, 2021). "In agreement, overexpression of ZnR/GPR39 in β-cells resulted in protection from streptozotocin-induced diabetes." (PMID 29389900, 2018). "The gene encodes a G protein-coupled receptor that has been shown before to be involved in regulating islet function, and that GPR39 agonists could be a potential therapeutic target for diabetes treatment." (PMID 38909044, 2024). "GPR39 has been reported to be down‐regulated in adipose tissue in obesity‐related diabetes." (PMID 29055040, 2017). "In view of the documented islet protective properties of GPR39, an agonist of GPR39 could potentially be useful in the treatment of diabetes where the β cells are under oxidative stress." (PMID 22164158, 2011). "In mice with streptozocin-induced diabetes, overexpression of GPR39, specifically in beta islet cells, protected against gradual hyperglycemia, even though GPR39 overexpression without streptozocin induced diabetes and appeared to impair glucose tolerance." (PMID 34360964, 2021).